COL5A2 (collagen type V alpha 2 chain)
Diseases named in the same sentence as COL5A2 in open-access papers (continued):
Sharing a sentence is not in itself a finding about the gene and the disease.
cancer (continued). "COL5A2 expression in cancer tissue was significantly higher than that in adjacent normal tissues (P<0.001)." (PMID 33739392, 2021). "A few reports have indicated COL5A2's role in the pathological process of cancers, including two studies that identified COL5A2 as a potential biomarker in BC." (PMID 30697528, 2018). "Whereas all of the assessed genes showed high expression in fibroblasts, several genes, including SPARC, ADAM12, TIMP2, MMP2, and COL5A2 were also expressed in carcinoma cells, albeit at lower levels." (PMID 27128408, 2016). "The top 20 up‐ and down‐regulated genes between malignant and mesothelial populations showed expected markers, such as PVRL4 or COL5A2, as well as genes that suggested a metabolically active cancer cell phenotype (WNT7B) and reactive mesothelial cells (MMP2 and LRP1) (upper heatmap)." (PMID 37691350, 2023). "This second cluster could represent a cancer-associated fibroblast (CAF) population characterized by low expression of MSLN and WT1 and high expression of ACTA2, S100A4, COL5A2, SPARC, and FN1." (PMID 36901697, 2023). "Collagen type V alpha 2 (COL5A2) is increased in various cancers, yet it remains unclear how it contributes to the prognosis and immunity of GC." (PMID 37723519, 2023). "In addition, the M genes that exhibited dynamic compartment changes across the cancer cell lines were enriched in the biological process related to anatomical structure morphogenesis, including COL5A2, LOX, CDH2, ZEB1, and AXL (FDRdynamic = 1.22 × 10−8)." (PMID 35637517, 2022). "However, the associations of other genes used in our model with ICI efficacy have not been reported, although some of them have been found to play critical roles in cancer, such as COL5A2, FAT2, ITPR3, PCDH20, and UTRN." (PMID 35557959, 2022). "Functional annotation demonstrated COL5A2 might be involved in the formation of the extracellular matrix, focal adhesion, and some cancer-related pathways." (PMID 33739392, 2021). "Although the authors hypothesize that COL11A1 forms a heterotrimer with COL5A2 at a 2:1, other combinations of these collagen alpha chains might be possible in a cancer type-specific manner." (PMID 33668097, 2021). "COL5A2 has different roles in predicting the prognosis of different cancers." (PMID 32819300, 2020). "It suggested that COL5A2 in these cancers could be an oncogene." (PMID 37723519, 2023). "Further, we analyzed COL5A2 expression in GC using UALCAN based on sample types, cancer stages, and grades with TCGA database." (PMID 36712590, 2023). "Further analysis of the correlation between these key genes and the pathological stage of GC showed that COL1A1, COL5A2, P4HA3, and SPARC were significantly correlated to cancer pathological stages." (PMID 35368700, 2022). "Summary of top four selected genes (COL5A2, ITGAV, SPARC and ACTA2) which were correlated with EMT signature in 32 pan cancer cohorts was presented in radar graphs, and the well-known CDH1 (Epithelial) and VIM (Mesenchymal) genes were included as controls." (PMID 35046456, 2022). "The expressions of BGN, COMP, COL5A2, and SPARC were further verified using scRNA-seq data between cancer and normal samples." (PMID 34899080, 2021). "The genome-wide co-expression analyses showed that the expression levels of collagen genes (COL1A1, COL1A2, COL5A1, COL5A2, COL8A1 and COL8A2) and LincRNAs (Linc01614 and Linc01711) were significantly positively correlated with PODNL1 expressions in various cancers." (PMID 37504302, 2023). "COL10A1 and COL5A2 are members of the collagen family, and the dysregulation of COL10A1 and COL5A2 may represent a basis for cancer invasion and migration." (PMID 33602210, 2021).
cancer (continued). "Collagen type V alpha 2 chain (COL5A2) has previously been reported to be involved in various pathological processes in tumorigenesis and cancer progression, such as cancer cell survival, migration, immune microenvironment, angiogenesis and blood vessel development." (PMID 34419075, 2021). "Besides VEGFA which was widely known and applied in anti-angiogenic therapy, in our pan-cancer analysis, some genes, like SPP1, STC1 and COL5A2, were not only highly expressed in most tumors, but also risk factors of prognosis." (PMID 36479101, 2022).
connective tissue disorder (10 papers, 2011 to 2025). A disease involving the connective tissue. "Classical Ehlers–Danlos syndrome (cEDS) is a connective tissue disorder mainly caused by heterozygous COL5A1 or COL5A2 variants encoding type V collagen and rarely by the p.(Arg312Cys) missense substitution in COL1A1 encoding type I collagen." (PMID 32720758, 2020). "EDS (Classic Type) is a hereditary connective tissue disorder characterized by joint hypermobility, skin hyperextensibility, and tissue fragility due to mutations in the COL5A1 or COL5A2 genes encoding type V collagen." (PMID 40110250, 2025).
cardiovascular diseases (1 paper, 2022). "In cardiovascular diseases, Col5a2 has an equally indispensable role." (PMID 35964009, 2022).
COL5A2 also shares sentences with these, for which no sentence is quoted: non-small cell lung carcinoma (3 papers); ductal carcinoma in situ (2); glioblastoma (2); melanoma (2); Obesity (2); oral cancer (2); adenocarcinoma (1); ameloblastoma (1); amoebiasis (1); aortic aneurysm (1); cervical artery dissection (1); cervical cancer (1); Chiari malformation type I (1); cholangiocarcinoma (1); Crohn disease (1); dermatosparaxis (1); diabetes (1); energy metabolism disorders (1); esophageal squamous cell carcinoma (1); Familial adenomatous polyposis (1); fibroids (1); fibromyalgia (1); fibrosis (1); glaucoma (1); heart disease (1); hematoma (1); hemochromatosis type 4 (1); ichthyosis (1); infarction (1); intracranial aneurysms (1).
A further 16 diseases each share a sentence with COL5A2 in 1 paper.